PADI4 (peptidyl arginine deiminase 4)
Diseases named in the same sentence as PADI4 in open-access papers (continued):
Sharing a sentence is not in itself a finding about the gene and the disease.
osteosarcoma (9 papers, 2012 to 2024). A usually aggressive malignant bone-forming mesenchymal neoplasm, predominantly affecting adolescents and young adults. "Then, we detected expression of PADI4 in human tissues of osteosarcoma and revealed that differential expression of PADI4 was associated with tumorigenesis of osteosarcoma." (PMID 34055985, 2021). "PADI4 promotes osteosarcoma cell invasion and migration through epithelial-mesenchymal transition (EMT); many studies have confirmed the carcinogenic role of PADI4 as a cancer susceptibility gene in a variety of cancers." (PMID 37804426, 2023). "Our present study has shown the upregulated expression of PADI4 in osteosarcoma tissues in comparison with the matched adjacent tissues." (PMID 34055985, 2021). "This study gives us new insight into the regulation mechanism of osteosarcoma proliferation and highlights PADI4 as a promising target for osteosarcoma diagnosis and treatment." (PMID 34055985, 2021). "Then, we studied the mechanism involved in the regulation of osteosarcoma proliferation mediated by PADI4." (PMID 34055985, 2021). "In order to investigate the role of PADI4 in osteosarcoma proliferation in clinical samples, we then analyzed the correlation between PADI4 expression and clinicopathological parameters." (PMID 34055985, 2021). "Next, we performed Western blot and RT-PCR to explore the relevance of PADI4 expression in osteosarcoma samples and paired normal tissues." (PMID 34055985, 2021). "Compared with normal tissues, the expression of PADI4 in osteosarcoma samples was significantly higher, which also supports our conclusions in cell experiments." (PMID 34055985, 2021). "The detection of cell viability using CCK8 methods clearly demonstrated that DKK1 overexpression reversed the promotion effect of PADI4 on osteosarcoma cell proliferation." (PMID 34055985, 2021). "Taken together, results of this work confirmed that PADI4 can promote osteosarcoma proliferation through Wnt/β-catenin and MEK/ERK signaling pathways." (PMID 34055985, 2021). "In order to further confirm the role of DKK1 in PADI4-mediated osteosarcoma cell proliferation, we transfected osteosarcoma cells with DKK1 plasmid together with PADI4 overexpression." (PMID 34055985, 2021). "Here, we first assessed the effect of PADI4 on osteosarcoma proliferation by the CCK8 method and colony formation assay." (PMID 34055985, 2021). "Tumor formation experiments in nude mice were performed to further confirm the role of PADI4 in osteosarcoma tumorigenesis in vivo." (PMID 34055985, 2021). "Next, we examined the mRNA and protein expression level of PADI4 in both osteosarcoma tissues and adjacent tissues." (PMID 34055985, 2021). "In conclusion, this work revealed that PADI4 could upregulate the proliferation of osteosarcoma, mainly via the Wnt/β-catenin and MEK/ERK signaling pathway." (PMID 34055985, 2021). "Firstly, we detected the protein expression of PADI4 in the normal human osteoblast cell (hFOB1.19) and several human osteosarcoma cell lines (U2OS, Saos-2, HOS, SJSA1, and 143B) by Western blot, and the results indicated increased PADI4 expression in osteosarcoma cells." (PMID 34055985, 2021). "In this work, we suggested that PADI4 could accelerate osteosarcoma progression, and the use of PADI4 inhibitors could effectively slow down the proliferation of osteosarcoma." (PMID 34055985, 2021). "Additionally, we also revealed that the upregulation of osteosarcoma proliferation by PADI4 is primarily through the Wnt/β-catenin and MEK/ERK signaling pathway." (PMID 34055985, 2021). "Furthermore, in order to confirm the regulation of the PADI4 inhibitor on the mRNA level of downstream genes of β-catenin, we also performed qRT-PCR assay in osteosarcoma cells." (PMID 34055985, 2021). "However, the effect and related mechanism of PADI4 on the progression of osteosarcoma remain largely unrevealed." (PMID 34055985, 2021).
osteosarcoma (continued). "This work gives us new insight into the mechanism exploration of osteosarcoma proliferation and indicated that PADI4 might serve as a promising target and biomarker for osteosarcoma diagnosis and therapy." (PMID 34055985, 2021). "However, the role of PADI4 on osteosarcoma tumorigenesis remains largely unrevealed." (PMID 34055985, 2021). "However, as in osteosarcoma progression, the effect of PADI4 remains largely unrevealed." (PMID 34055985, 2021). "PADI4 could promote osteosarcoma cell proliferation both in vitro and in a mouse xenograft model." (PMID 34055985, 2021). "It is shown that PADI4, p-ERK, and active β-catenin had higher expression levels in osteosarcoma tissues than in adjacent normal tissues in these mice." (PMID 34055985, 2021). "Results showed increased staining of PADI4, p-ERK, and active β-catenin in osteosarcoma tissues compared with adjacent normal tissues." (PMID 34055985, 2021). "As Wnt/β-catenin and MEK/ERK signaling was involved in the tumorigenesis of several human tumors and bone development, next, we assessed the effect of PADI4 on the activity of Wnt/β-catenin and MEK/ERK signaling in osteosarcoma cells." (PMID 34055985, 2021). "In addition, the PADI4 mutant without enzyme activity did not change the colony-forming ability of osteosarcoma cells, indicating that the enzyme activity of PADI4 is essential to regulate the proliferation of osteosarcoma cells." (PMID 34055985, 2021).
pancreatic cancer (9 papers, 2009 to 2023).
colon cancer (8 papers, 2009 to 2023). "Targeting PADI4 either via RNAi or the inhibitor Cl-amidine can induce differentiation of HT29 colon cancer cells." (PMID 33363159, 2020).
esophageal cancer (8 papers, 2009 to 2025). A primary or metastatic malignant neoplasm involving the esophagus. "In a small cohort of esophageal cancer patients (including ESCC and EAC), PADI4 rs10437048 and rs41265997 were found significantly associated with the risk of esophageal cancer." (PMID 29212180, 2017). "We previously reported that the haplotype GC, which contains rs2501796 and rs2477134 in the PADI4 locus, was significantly associated with an increased risk of esophageal carcinoma." (PMID 27556695, 2016). "In addition, we found that elevated PADI4 levels are positively correlated with the pathological classification of esophageal squamous cell carcinoma and that the PADI4 gene has a valid susceptibility to the risk of esophageal carcinoma." (PMID 27556695, 2016). "Based on our prior research on chemotherapy resistance in OSCC and comprehensive database analyses, we curious the potential role for PADI4 in influencing cisplatin resistance and stemness in oesophageal cancer." (PMID 40078091, 2025). "We used cultured esophageal cancer (EC) cells with overexpression of PADI4 or used a recombinant PADI4 protein as a tumor antigen to load DCs in DC-CIK cell immunotherapy of mouse-burden EC." (PMID 30944835, 2019). "Significantly, PADI4 levels were positively correlated with the pathological classification of esophageal cancer." (PMID 29212180, 2017). "Our studies and others have demonstrated that PADI4 expression is increased in many human tumor tissues, including cervical squamous cell carcinoma, gastric carcinoma, lung cancer, ovarian serous papillary adenocarcinoma, thyroid papillary carcinoma, and esophageal cancer." (PMID 30944835, 2019). "Therefore, we postulated that PADI4 might play an important role in the carcinogenesis of the esophageal cancer." (PMID 29212180, 2017). "Furthermore, expression of PADI4 was detected in esophageal cancer, but not in normal tissues." (PMID 29212180, 2017).
acute pancreatitis (7 papers, 2009 to 2025). An acute inflammatory process that leads to necrosis of the pancreatic parenchyma. "PSGL-1-P-selecitn interaction has been reported to induce NET formation in a peptidyl arginine deiminase 4 (PAD4)-dependent manner in acute pancreatitis." (PMID 40226627, 2025).
ulcerative colitis (7 papers, 2019 to 2025). An inflammatory bowel disease involving the mucosal surface of the large intestine and rectum. "Pharmacological or genetic perturbation of PADI4 in mice alleviates the development of RA and ulcerative colitis, while Padi4-null mice are protected against NET-associated tissue destruction in a wide variety of contexts." (PMID 39528459, 2024).
ischemic stroke (6 papers, 2022 to 2026). A stroke disorder caused by obstruction of blood flow to the brain, due to thrombotic (local blood clot formation) or embolic (due to a blood clot or other material traveling from another site) event. "Balancing NET activity through targeted therapies—such as peptidyl arginine deiminase 4 (PAD4) inhibitors or deoxyribonuclease I (DNase I)—holds promise for treating ischemic stroke and other NET-related disorders." (PMID 41018178, 2025). "DNase I and deficiency of peptidyl arginine deiminase 4 (PAD4), which can inhibit NETs, reversed tPA-mediated upregulation of cGAS.However, cGAMP application suppressed DNase I-mediated antihemorrhagic effects by downregulating the STING and INF in tPA-treated mice following ischemic stroke." (PMID 36304999, 2022).
Alzheimer disease (5 papers, 2019 to 2025). A progressive, neurodegenerative disease characterized by loss of function and death of nerve cells in several areas of the brain leading to loss of cognitive function such as memory and language. "More important is documentation that PADI4 is expressed in both neurons and astrocytes of the hippocampus and cortex in human brain, and may contribute to formation of autoantibodies in Alzheimer’s disease." (PMID 34573423, 2021).
esophageal squamous cell carcinoma (5 papers, 2009 to 2023). Esophageal squamous cell carcinoma (ESCC) is a type of esophageal carcinoma (EC) that can affect any part of the esophagus, but is usually located in the upper or middle third. "PADI4 also promotes tumorigenesis and metastasis in esophageal squamous cell carcinoma by upregulating carbonic anhydrase 9 (CA9) expression." (PMID 37804426, 2023). "In esophageal squamous cell carcinoma (ESCC), PADI4 can stimulate the growth of ESCC cells and upregulate CA9 to promote ESCC metastasis." (PMID 37020554, 2023).
lung adenocarcinoma (5 papers, 2009 to 2023). A carcinoma that arises from the lung and is characterized by the presence of malignant glandular epithelial cells. "We also examined PADI4 expression in cultured lung adenocarcinoma (A549), ovarian adenocarcinoma (SKOV3), and leukemia (U937) cell lines." (PMID 19183436, 2009).
nephritis (5 papers, 2019 to 2023). Inflammation of renal tissue. "In preclinical studies, inhibition of peptidyl arginine deiminase 4 (PAD4), an enzyme playing an important role in NET formation, has been found to exert a favorable effect in nephritis mouse models." (PMID 37047548, 2023). "This conclusion is reinforced by prior work from our group and that of others targeting PADI4 in SLE and nephritis models that yielded similar results." (PMID 32243431, 2020).
non-small cell lung carcinoma (5 papers, 2018 to 2023). A group of at least three distinct histological types of lung cancer, including non-small cell squamous cell carcinoma, adenocarcinoma, and large cell carcinoma. "It is reported that cell free circulation PADI4 mRNA level (together with cfDNA, PPBP, and haptoglobin) in peripheral blood of non-small cell lung cancer patients was significantly higher than that in healthy donors, so PADI4 may serve as a potential marker for NSCLC diagnosis." (PMID 29915691, 2018). "In non-small cell lung cancer (NSCLC), the overexpression of PADI4 can downregulate the expression of ETS domain protein (Elk1) and inhibit EMT, thereby reducing the drug resistance of NSCLC." (PMID 37020554, 2023). "Additionally, PADI4 has been suggested to act as a tumour suppressor as Padi4-null mice showed resistance to DNA damage-induced apoptosis in the thymus and H4R3 citrullination was associated with smaller tumour size in a cohort of non-small cell lung carcinoma patients." (PMID 35706669, 2022).
bladder carcinomas (4 papers, 2009 to 2022). "Moreover, it has been demonstrated that PADI4 expression is increased in the peripheral blood of patients with lung, breast, colorectal and bladder cancer, highlighting its potential involvement in the process of tumorigenesis." (PMID 23468981, 2013).
breast tumor (4 papers, 2016 to 2021). "It is possible that both PADI2 and PADI4 are expressed in breast tumor tissues and function by different pathogenic pathways." (PMID 27478411, 2016).
Hyperglycemia (4 papers, 2023 to 2025). An increased concentration of glucose in the blood. "DNase I treatment or Padi4 gene deficiency abolishes NETs formation in the intestinal epithelium and mitigates intestinal epithelial barrier impairment in the hyperglycemic mice, supporting the causal relationship between NETs and hyperglycemia-associated intestinal epithelial barrier impairment." (PMID 40098957, 2025). "In diabetic Padi4-/- mice, there is no delayed wound healing, showing that hyperglycemia triggers neutrophils to overproduce PAD4 and NETs, revealing NETs as a deterrent component in slowing down wound healing." (PMID 37600700, 2023).
malignant lymphoma (4 papers, 2009 to 2023). "Furthermore, PADI4 was also expressed in over 40% of cells in malignant lymphomas (IRS ≥ 8)." (PMID 19183436, 2009).
metastatic carcinoma (4 papers, 2009 to 2022). A carcinoma which has spread from the original site of growth to another anatomic site. "PADI4 is overexpressed in numerous malignant cancers (e.g., breast, metastatic carcinomas, colon, bladder, lung, ovarian, and many others)." (PMID 29212180, 2017).
juvenile idiopathic arthritis (3 papers, 2017 to 2023). Juvenile idiopathic arthritis (JIA) is the term used to describe a group of inflammatory articular disorders of unknown cause that begin before the age of 16 and last over 6 weeks. "PADI4 polymorphisms confer susceptibility to OA and juvenile idiopathic arthritis (JIA)." (PMID 37020554, 2023).
lupus nephritis (3 papers, 2019 to 2022). Glomerulonephritis in the context of systemic lupus erythematosus. "One recent study also suggests an association with PADI4 gene polymorphisms and patients with SLE with additional PADI4 polymorphisms conferring an increased risk of renal involvement in the form of lupus nephritis." (PMID 30712132, 2019). "These genetic studies supported the importance of PADI4 in the pathogenesis of human lupus nephritis, and further human studies are required for unveiling the precise roles of PADI4 in human diseases." (PMID 32655553, 2020). "Peptidylarginine deiminase 4 (PAD4), encoded by PADI4, plays critical roles in the immune system; however, its contribution to the pathogenesis of lupus nephritis remains controversial." (PMID 32655553, 2020).
mastitis (3 papers, 2019 to 2025). Inflammation of breast tissue during lactation or postpartum due to an obstructed duct or infection. "Additionally, PADI4 has been found as a putative candidate marker for susceptibility to subclinical mastitis in Norwegian Red cattle." (PMID 38486242, 2024). "This suggests the possibility that PADI4 might display a role in the susceptibility to subclinical mastitis and that low GEBV animals may have impaired neutrophil responses to infection." (PMID 31417606, 2019).
metastatic tumour (3 papers, 2020 to 2022). "PADI4 is detected in the blood of cancer patients and in a large array of malignant tumours whose normal tissue and benign tumour counterparts lack PADI4 expression, while metastatic tumours exhibit significantly higher PADI4 expression than the corresponding primary tumours." (PMID 35706669, 2022).
nasopharyngeal carcinoma (3 papers, 2022 to 2024). A carcinoma arising from the nasopharyngeal epithelium. "In a study, peptidyl arginine deiminase 4 (PAD4) is identified as nasopharyngeal carcinoma (NPC) biomarker, negatively regulated by microRNA 3,164 (miR-3164)." (PMID 36034776, 2022). "In nasopharyngeal carcinoma, PADI4 can activate the PI3K/AKT pathway to promote proliferation." (PMID 37020554, 2023).
Obesity (3 papers, 2021 to 2025). Accumulation of substantial excess body fat. "In the HFD-induced obesity model in male mice, deletion of PAD4 in hematopoietic cells (Padi4KO) or pharmacologic inhibition of PADI4 by the selective PADI4 inhibitor GSK484 did not affect body weight gain or fat accumulation." (PMID 41550876, 2025).
osteoarthritis (3 papers, 2009 to 2023). A noninflammatory degenerative joint disease occurring chiefly in older persons, characterized by degeneration of the articular cartilage, hypertrophy of bone at the margins and changes in the synovial membrane. "Together with PADI4, the protein level of PADI2 was reported to be highly increased in RA synovial tissues compared with that in samples from patients with osteoarthritis and ankylosing spondylitis, and some SNPs of the PADI2 gene were shown to be significantly associated with the presence of RA." (PMID 35218410, 2022).
pancreatitis (3 papers, 2016 to 2020). Inflammation of the pancreas. "Strikingly,PADI4 deficiency strongly protected mice from the development ofIL-17A-induced pancreatitis: signsof fibroinflammatory remodelling such as pseudotubular complex formation andacinar cell loss were absent." (PMID 26964500, 2016). "In summary, both acute caerulein-induced pancreatitis and its progression tochronicity occur independently of PADI4." (PMID 26964500, 2016).
preeclampsia (3 papers, 2012 to 2023). Preeclampsia is a hypertensive disorder of pregnancy that is characterized by new-onset hypertension with proteinuria presenting after 20 weeks of gestation, and depending on mild or severe forms may initially present with severe headache, visual disturbances, and hyperreflexia. "It is through suppressing the NEMO/NF-κB pathway that peptidyl arginine deiminase 4 knockdown inhibits inflammation in trophoblast cells to reduce preeclampsia development in vitro." (PMID 37505866, 2023).
septic shock (3 papers, 2018 to 2025). Shock caused by infection; frequently caused by gram negative bacteria, although some cases have been caused by other bacteria, viruses, fungi, and protozoa; characterized by fever, chills, tachycardia, tachypnea, and hypotension. "In conclusion, PAD4 concentration, but not PADI4_89, PADI4_94 and PADI4_104 polymorphisms, is associated with ICU mortality in septic shock patients." (PMID 30044533, 2018).
Shock (3 papers, 2018 to 2024). The state in which profound and widespread reduction of effective tissue perfusion leads first to reversible, and then if prolonged, to irreversible cellular injury. "In Brazilian patients with septic shock, the SNP rs11203366 of PADI4 did not affect patient mortality." (PMID 38524554, 2024).
airway hyperresponsiveness (2 papers, 2022 to 2025). "Surprisingly, the lung resistance in LPS+ OVA group of Padi4-/- mice was significantly higher than that of Csf3-/-mice, suggesting that, beyond NETs, additional neutrophil functions may contribute to airway hyperresponsiveness." (PMID 40963601, 2025). "In Padi4-/-mice, we established a conventional model of allergic asthma via OVA sensitization and challenge, characterized by inflammatory cell infiltration, goblet cell hypersecretion, and airway hyperresponsiveness." (PMID 40963601, 2025).
aneurysm (2 papers, 2023 to 2024). Bulging or ballooning in an area of an artery secondary to arterial wall weakening. "High expression of PADI4 was associated with a high risk of rupture and large aneurysm size." (PMID 37121969, 2023).
cervical cancer (2 papers, 2009 to 2024). A primary or metastatic malignant neoplasm involving the cervix. "Finally, PADI4 levels were found to be significantly increased in the blood of patients with cervical cancer." (PMID 38529474, 2024).